HDAC10 (histone deacetylase 10)
Diseases named in the same sentence as HDAC10 in open-access papers (continued):
Sharing a sentence is not in itself a finding about the gene and the disease.
breast carcinoma (5 papers, 2021 to 2025). "The log-rank P values were all less than 0.05, suggesting that patients with high expression of PAK1 and HDAC6/10 had higher mortality rates than those with low expression, indicating the potential of PAK1 and HDAC10 as therapeutic targets for breast cancer." (PMID 40302782, 2025). "First, we examined the levels of PAK1, HDAC6, and HDAC10 in breast cancer tissues at different disease stages." (PMID 40302782, 2025). "We observed variations in the expression levels of HDAC1, HDAC2, HDAC3 and HDAC10 mRNAs targeted by chidamide among the ER+ breast cancer cell lines." (PMID 37445654, 2023). "Additionally, analysis of sequencing data from 1,462 breast cancer patients revealed a significant correlation between HDAC10 expression levels and patient prognosis." (PMID 40091020, 2025). "Chidamide, a selective inhibitor targeting HDAC1, HDAC2, HDAC3, and HDAC10, has been approved for treating relapsed/refractory peripheral T cell lymphoma and hormone receptor-positive, HER2-negative breast cancer after endocrine therapy." (PMID 41049003, 2025). "Our findings revealed that the levels of PAK1 and HDAC10 were elevated compared to those observed in individuals without breast cancer across various stages of the disease, while the expression level of HDAC6 displayed no significant change." (PMID 40302782, 2025).
glioma (5 papers, 2015 to 2022). A benign or malignant brain and spinal cord tumor that arises from glial cells (astrocytes, oligodendrocytes, ependymal cells). "The CNVs for the other four LARs–KAT6B (10q), SIRT1(10q), HDAC10 (22q), and HDAC9 (7q)–were highly associated with the risk signature and may be affected in chromosomal alterations such as 10q−, 22q− and 7+ in gliomas." (PMID 33718432, 2021). "Except for HDAC6 (p = 0.367), HDAC9 (p = 0.870), and HDAC10 (p = 0.715), the majority of HDAC family expression levels correlated significantly with glioma grade." (PMID 34540896, 2021). "HDAC6 expression was significantly increased in all gradesof gliomas, whereas HDAC7 and HDAC10 were significantly increasedonly in ODIII and GL tumors." (PMID 25791281, 2015). "HDAC10 expression is moderate in LGG and elevated in high-grade gliomas." (PMID 35359455, 2022). "However, low HDAC10 mRNA expression was not significantly correlated with DFS in patients with glioma." (PMID 35359455, 2022).
colon cancer (4 papers, 2021 to 2025). "A study of colon cancer patients in China reported constitutively elevated expression of HDAC10 protein in tumor tissues compared to paired adjacent tissue in the majority of patients, with the greatest difference observed in cytoplasmic HDAC10." (PMID 35988653, 2022). "We therefore extended our recent studies using HDAC10-selective inhibitors to determine if inhibiting deacetylase activity was sufficient to prevent polyamine restoration and growth rescue by N8-AcSpd in HCT116 colon cancer cells." (PMID 35988653, 2022). "HDAC10 also regulates angiogenesis via depletion of VEGFR in gastric and colon cancer cells." (PMID 33997894, 2021). "We found that inhibition of HDAC4, but not HDAC10, down-regulates the mRNA level of YAP and MybL1 in prostate and colon cancer cells." (PMID 41281751, 2025).
colorectal cancer (4 papers, 2019 to 2022). A primary or metastatic malignant neoplasm that affects the colon or rectum. "In human colorectal cancer, HDAC10 expression is associated with DNA mismatch repair genes." (PMID 32373519, 2020). "In colorectal cancer, inhibited HDAC10 expression promotes cell apoptosis by depleting transcription factor 7 like 2 (TCF7L2), which attenuates the Wnt pathway." (PMID 33997894, 2021). "In colorectal cancer cells, TSA induces the inhibition of HDAC10 as well as HDAC6, and subsequently attenuates the Wnt pathway by the deletion of the Wnt signaling pathway-associated factor TCF7L2 in a proteasome-dependent way, which suppresses cell proliferation in vitro." (PMID 33997894, 2021).
leukemia (4 papers, 2023 to 2025). A malignant (clonal) hematologic disorder, involving hematopoietic stem cells and characterized by the presence of primitive or atypical myeloid or lymphoid cells in the bone marrow and the blood. "Our data reveal that human leukemia cells of the lymphoid lineage and lymphomas cells succumb to HDAC10 inhibition, elucidate the underlying molecular mechanisms, and disclose pharmacodynamic markers to assess anti-leukemic activities of HDAC10 inhibitors." (PMID 40301616, 2025). "To further clarify the relationship between Periplocin, HDAC10, and P-P65, we examined P-P65 expression in HDAC10 knockdown leukemia cell lines." (PMID 40657362, 2025). "The Human Protein Atlas database illustrates that of various human tumor cell lines analyzed, leukemia and lymphoma cells have the highest HDAC10 mRNA expression levels." (PMID 40301616, 2025). "This phenotype closely mirrors the pro-apoptotic effect observed following Periplocin treatment, suggesting that HDAC10 downregulation is a key mechanism contributing to Periplocin-induced apoptosis in leukemia cells." (PMID 40657362, 2025). "By validating HDAC10 expression at both the transcriptional and protein levels, we propose that HDAC10 is a key target through which Periplocin exerts its anti-leukemia effects." (PMID 40657362, 2025). "Chidamide is an oral selective histone deacetylase (HDAC) inhibitor that selectively inhibits HDAC1, HDAC2, HDAC3, and HDAC10, inducing apoptosis and growth arrest in leukemia cells." (PMID 39040100, 2024). "The biologically relevant functions of HDAC10 in leukemia cells are enigmatic." (PMID 40301616, 2025). "To clarify if HDAC10 controls leukemia cell fate, we applied the HDAC10 inhibitor PZ48 to human leukemia cells and determined apoptosis by flow cytometry." (PMID 40301616, 2025). "To scrutinize the interplay between HDAC10 and POLD1 expression, we assessed their levels by immunoblot in various leukemia cell types that were incubated with PZ48." (PMID 40301616, 2025). "The same experiment performed using the leukemia cell line MV4-11 validated HDAC1 (Kdapp = 16 μM), HDAC2 (Kdapp = 14 μM), and HDAC6 (Kdapp = 21 μM) and identified HDAC3 (Kdapp = 13 μM) and HDAC10 (Kdapp = 5 μM) as additional targets of (R/S)-LM." (PMID 37322067, 2023).
non-small cell lung carcinoma (4 papers, 2020 to 2025). A group of at least three distinct histological types of lung cancer, including non-small cell squamous cell carcinoma, adenocarcinoma, and large cell carcinoma. "HDAC10 expression is positively associated with PD-L1 expression and may predict the outcome of patients with non-small cell lung carcinoma." (PMID 35359455, 2022). "HDAC10 expression was also described in malignancies, for example, non-small cell lung carcinoma (NSCLC) and melanoma." (PMID 39958888, 2025).
bladder cancer (3 papers, 2022 to 2025). "Such a MYC-POLD1 signaling axis also occurs in bladder cancer, suggesting that further tumor cell types could be susceptible to HDAC10 inhibitors." (PMID 40301616, 2025). "Immunohistochemistry of bladder cancer samples also demonstrated that HDAC10 expression was also significantly elevated in NSUN6‐high samples." (PMID 37408139, 2023).
colitis (3 papers, 2019 to 2022). Inflammation of the colon. "That said, Treg are likely to play a somewhat important role, considering that the origin of Tregs (HDAC10−/− vs WT) was the only variable in the colitis prevention model." (PMID 31949209, 2020). "By day 33, the mice had developed colitis and weight loss, and were randomly assigned to receive 5 × 105 Treg i.p. from either WT or HDAC10−/− donor mice for colitis rescue." (PMID 31949209, 2020). "We conclude that targeting of HDAC10 may be of therapeutic value for inflammatory disorders including colitis and also for transplantation." (PMID 31949209, 2020). "Furthermore, transfer of Treg cells from HDAC10 knock-out mice in a colitis mouse model resulted in a reduced induction of colitis compared to transfer of wild-type (WT) Treg cells." (PMID 30792714, 2019). "C57BL/6 Rag1−/− mice adoptively transferred with HDAC10−/− but not wild Treg, were protected from developing colitis." (PMID 31949209, 2020). "In the colitis prevention model, B6/Rag1−/− mice were adoptively transferred i.p. with 1 × 106 WT CD4+CD25− Tconv together with 5 × 105 CD4+CD25+ Treg from either WT or HDAC10−/− donors simultaneously." (PMID 31949209, 2020). "This was matched by less inflammation upon histologic examination, whereby colon samples from B6/Rag1−/− mice receiving WT, but not HDAC10−/− Treg showed more prominent colitis including transmural inflammation, ulceration, reactive epithelial changes and crypt abscesses." (PMID 31949209, 2020). "Moreover, it was noticed that Treg cells with a lack of HDAC10 alleviated the colitis using in vivo models, which could indicate that HDAC10 deletion possibly had an immunosuppressive effect." (PMID 35887172, 2022).
hepatocellular carcinoma (3 papers, 2015 to 2024). A malignant tumor that arises from hepatocytes. "In a population-based study examining HDAC10 polymorphisms it was found that one variant that resulted in increased expression of HDAC10 protein also corresponded with an increased occurrence and accelerated onset of hepatocellular carcinoma in patients with chronic hepatitis B infection." (PMID 25915736, 2015). "The participation of HDAC10 in the HCV life cycle was previously unknown; however, an important consequence of the simultaneous inhibition of HDAC6 and HDAC10 by tubastatin A is the preservation of the antiviral activity of the drug during the conversion from RP to PS hepatoma cells." (PMID 33925399, 2021).
HIV-1 infection (3 papers, 2019 to 2024). The type species of lentivirus and the etiologic agent of acquired immunodeficiency syndrome (AIDS). "HDAC10 levels are reduced during HIV-1 infection due to the activity of the envelope glycoprotein associated with the virus." (PMID 39599797, 2024). "HDAC10 is downregulated during HIV-1 infection due to the activity of virus-associated envelope glycoprotein." (PMID 36293197, 2022). "Knockdown of HDAC10 in CD4+ T cells by specific shRNAs has been shown to enhance HIV-1 infection, in particular by facilitating the integration stage." (PMID 39599797, 2024). "Knockdown of HDAC10 in CD4+ T cells with specific shRNAs was shown to benefit HIV-1 infection, specifically facilitating an integration step." (PMID 36293197, 2022). "After demonstrating the downregulation of HDAC10 during HIV-1 infection, we next investigated the effect of HDAC10 downregulation on HIV-1 infection and replication." (PMID 31888084, 2019). "Next, we checked the HDAC10 expression changes upon HIV-1 infection in primary CD4+ T cells." (PMID 31888084, 2019).
pancreatic cancer (3 papers, 2019 to 2022). "In our analysis, the CN gains of ESCO2 and HDAC10 were found to be risk factors for colorectal and pancreatic cancer, respectively." (PMID 35422864, 2022). "A recent analysis of TCGA data reported HDAC10 copy number gains as a risk factor for colorectal and pancreatic cancers." (PMID 35988653, 2022).
peripheral T cell lymphoma (3 papers, 2022 to 2025). "Chidamid, an oral HDAC inhibitor of the benzamide class with specificity for HDAC1, HDAC2, HDAC3, and HDAC10 subtypes, has been approved for the treatment of relapsed or refractory peripheral T cell lymphoma." (PMID 41049003, 2025). "We chose to use tucidinostat (chidamide), a selective inhibitor of class I HDAC1−HDAC3 and class IIb HDAC10, which has been clinically approved for peripheral T-cell lymphoma and adult T-cell leukemia-lymphoma." (PMID 36690761, 2023). "Tucidinostat, a selective HDAC inhibitor having specificity for HDAC1, HDAC2, HDAC3, and HDAC10 subtypes, has been approved for the treatment of relapsed or refractory peripheral T cell lymphoma and is under clinical development globally for various other neoplastic and non-neoplastic diseases." (PMID 36352411, 2022).
renal carcinoma (3 papers, 2020 to 2022). A carcinoma arising from the epithelium of the renal parenchyma or the renal pelvis. "For HDAC10, moderate staining patterns were positive on the cell membrane and nuclear of tubules cells in normal kidney tissues, but as for renal cancer samples, the high staining was observed on these cellular structures." (PMID 34308568, 2021).
renal cell carcinoma (3 papers, 2021 to 2023). "In renal cell carcinoma (RCC), overexpressed HDAC10 restrains RCC cell invasion by inhibiting phosphorylated nuclear β-catenin expression." (PMID 33997894, 2021).
acute myeloid leukemia (2 papers, 2025). Acute myeloid leukemia (AML) is a group of neoplasms arising from precursor cells committed to the myeloid cell-line differentiation. "The results revealed that HDAC10 expression in hematopoietic stem cells (HSCs) and early progenitor populations (e.g., GMP, CMP, MEP) is significantly lower than that observed in various acute myeloid leukemia subtypes." (PMID 40657362, 2025).
lymphoma (2 papers, 2019 to 2025). A malignant (clonal) proliferation of B- lymphocytes or T- lymphocytes which involves the lymph nodes, bone marrow and/or extranodal sites. "We demonstrate that human cultured and primary acute B cell/T cell leukemia and lymphoma cells require the catalytic activity of HDAC10 for their survival." (PMID 40301616, 2025). "Analyzing the database DepMap, we noted a significant correlation (Pearson r = 0,781; Spearman ρ = 0,671; p = 0.000004) between the expression of HDAC10 and POLD1 in 32 human lymphoblastic leukemia and lymphoma cell lines." (PMID 40301616, 2025).
prostate carcinoma (2 papers, 2019 to 2025). A carcinoma that arises from epithelial cells of the prostate gland. "Chidamide, in contrast, selectively targets HDAC1, HDAC2, HDAC3, and HDAC10, aligning closely with the four HDAC isoforms most overexpressed in prostate cancer, making it a more biologically relevant candidate for mCRPC treatment." (PMID 41200281, 2025).
renal fibrosis (2 papers, 2021 to 2022). A final common manifestation of a wide variety of chronic kidney diseases characterized by glomerulosclerosis and tubulointerstitial fibrosis. "HDAC10 is also a latent biomarker in immunoglobulin A nephropathy (IgAN) and renal fibrosis as well." (PMID 33997894, 2021). "Although HDAC10, another isoform of class IIb HDACs, has also been reported to be elevated in the kidney after UUO injury, its role in renal fibrosis remains unclear due to lack of HDAC10-specific inhibitor(s)." (PMID 35559244, 2022). "However, piceatannol treatment does not diminish HDAC10 expression but the results hint that HDAC10 may regulate renal fibrosis via other signaling pathways." (PMID 33997894, 2021).
schizophrenia (2 papers, 2021 to 2023). A major psychotic disorder characterized by abnormalities in the perception or expression of reality. "There are also some suggestions that HDAC10 might be, among others, a potential target for schizophrenia because of a single nucleotide polymorphism (SNP) (rs 7634112) located in the HDAC10 gene associated with schizophrenia." (PMID 36979236, 2023). "They devised a model that incorporates HDAC10, HDAC3 and HDAC9 to divide schizophrenia patients with high accuracy." (PMID 33997894, 2021).
silicosis (2 papers, 2024 to 2025). Silicosis is a respiratory disease caused by breathing in (inhaling) silica dust. "This antioxidant and anti-inflammatory role positions HDAC10 as a potential therapeutic target for silicosis-induced PF." (PMID 40343260, 2025). "HDAC10, as an upstream regulatory factor of ROS in silicosis, inhibits the accumulation of ROS by modulating protein acetylation, thereby suppressing the ROS/NF-κB signaling axis." (PMID 40343260, 2025). "Further, a newly published study demonstrated that nebulized inhalation of HDAC10 attenuates oxidative stress, inflammation, and pulmonary fibrosis in a murine model of silicosis, suggesting an anti-inflammatory role of HDAC10 in lung injury." (PMID 38397377, 2024). "Histone deacetylase 10 (HDAC10) has emerged as a regulator of oxidative stress and inflammation in silicosis." (PMID 40343260, 2025).
asthma (1 paper, 2023). "Upregulation of HDAC10 was positively associated with disease severity of asthma." (PMID 37441601, 2023). "Together, these findings suggested that HDAC10 was highly expressed in M2 macrophages and potentially promoted airway inflammation, which also prompted us to further explore the precise role of macrophage HDAC10 in airway inflammation process in asthma." (PMID 37441601, 2023). "To further determine the role of HDAC10 in the pathogenesis of asthma, we detected HDAC10 expression in the lung tissue in an experimental model of asthma." (PMID 37441601, 2023). "To investigate the mechanisms by which HDAC10 regulates STAT3 in asthma, we have therefore completed a series of experiments." (PMID 37441601, 2023). "In this study, we performed experiments in patients and animals to investigate the role of histone deacetylase HDAC10 on the pathogenesis of asthma." (PMID 37441601, 2023). "Both genetic and pharmacological inhibition of HDAC10 protect against airway inflammation in asthmatic mice, suggesting that the HDAC10/STAT3 axis is a potential target for treatment of asthma." (PMID 37441601, 2023). "Asthma was induced by exposure to allergen in mice with myeloid-specific deletion of Hdac10 (Hdac10fl/fl-LysMCre) mice." (PMID 37441601, 2023). "Our data indicated that HDAC10 inhibition might represent a valuable therapeutic approach for asthma." (PMID 37441601, 2023). "Collectively, these findings suggested that inhibition of HDAC10 with SAB treatment may be of potential value in the treatment of airway inflammation in asthma." (PMID 37441601, 2023). "However, whether and how HDAC10 regulates the pathogenesis of asthma have not been reported." (PMID 37441601, 2023). "However, whether and how HDAC10 regulates macrophage homeostasis in asthma has not been deciphered." (PMID 37441601, 2023).
autoimmune disease (1 paper, 2020). A disorder resulting from loss of function or tissue destruction of an organ or multiple organs, arising from humoral or cellular immune responses of the individual to their own tissue constituents. "We questioned if the increased HDAC10−/− Treg suppressive function observed in our in vitro studies translated into in vivo models of autoimmune disease and transplantation." (PMID 31949209, 2020).
bladder (1 paper, 2019). "HDAC10 had a low score for TFBSs associated with muscle tissue, while HDAC11 had a high score for TFBSs associated with the gall bladder." (PMID 31351464, 2019).
cervical squamous cell carcinoma (1 paper, 2020). A squamous cell carcinoma arising from the cervical epithelium. "It has been described that patients with lymph node metastasis have shown reduced expression of HDAC10 (class IIb) compared to those without metastatic prognosis in human cervical squamous cell carcinoma." (PMID 33634093, 2020).
chondrosarcoma (1 paper, 2020). A malignant cartilaginous matrix-producing mesenchymal neoplasm arising from the bone and soft tissue. "Of note, the expression of HDAC2, HDAC7, and HDAC10 seemed to be increased in chondrosarcoma cell lines as compared to healthy human cartilage, and romidepsin targets one of these subtypes (i.e., HDAC2)." (PMID 33266275, 2020).
chromophobe carcinoma (1 paper, 2021). "For example, in RCC (including chromophobe carcinoma, ccRCC, and papillary cell carcinoma), low expression of HDAC1, HDAC2, HDAC3, HDAC8, HDAC10 and high expression of HDAC5, HDAC7, HDAC11 have longer survival time." (PMID 34308568, 2021).